RHBDD1 (rhomboid domain containing 1)
Diseases named in the same sentence as RHBDD1 in open-access papers (continued):
Sharing a sentence is not in itself a finding about the gene and the disease.
lung carcinoma (2 papers, 2020 to 2024). "In contrast, miR-924 is a tumor suppressor in hepatocarcinoma cells and lung cancer, which inhibits the RHBDD1/Wnt/β-catenin signaling pathway." (PMID 38338859, 2024). "In this study, we analyzed the expression of miR-924 and its clinicopathological implication in NSCLC as well as the expression of RHBDD1 and its prognostic value in lung cancer patients." (PMID 33041671, 2020). "The expression level of RHBDD1 was evaluated in lung cancer tissues using public microarray datasets form Oncomine and its prognostic value was assessed by Kaplan–Meier Plotter databases." (PMID 33041671, 2020). "Total four online microarray datasets were included our analysis, which consistently indicated that the expression of RHBDD1 mRNA was significantly up-regulated in lung cancer tissues compared with the normal lung tissues (gene median rank: 5006.0, p = 1.78E−4)." (PMID 33041671, 2020).
Alzheimer disease (1 paper, 2018). A progressive, neurodegenerative disease characterized by loss of function and death of nerve cells in several areas of the brain leading to loss of cognitive function such as memory and language. "For example, RHBDD1 is an important protease and cleaves several different substrates, including BIK, a proapoptotic member of the Bcl-2 family, and the amyloid precursor protein, a key molecule in the etiology of Alzheimer disease." (PMID 30286765, 2018).
breast tumor (1 paper, 2018). "showed, the immunohistochemical data revealed that in breast tumor tissue, the cellular localization of RHBDD1 was restricted to both plasma membrane and cytoplasm." (PMID 30286765, 2018). "Our data demonstrate the clinical importance of RHBDD1 up-regulation in breast tumor tissue." (PMID 30286765, 2018).
colitis (1 paper, 2015). Inflammation of the colon. "To support the role of RHBDD1 in CRC and to substantiate the functional link between RHBDD1 and the EGFR signalling pathway, we performed confirmatory experiments in a murine model of colitis-associated CRC." (PMID 26300397, 2015).
esophageal cancer (1 paper, 2025). A primary or metastatic malignant neoplasm involving the esophagus. "In a xenograft mouse model, the influence of RHBDD1 on the proliferation of esophageal cancer was further confirmed." (PMID 40787199, 2025). "Despite these advancements in understanding RHBDD1’s role in multiple malignancies, its precise function and molecular mechanisms in esophageal cancer remain largely unexplored." (PMID 40787199, 2025). "Investigating the effects of RHBDD1 on esophageal cancer, we established cell lines that exhibited either di-minished or amplified expression of RHBDD1." (PMID 40787199, 2025).
esophageal squamous cell carcinoma (1 paper, 2025). Esophageal squamous cell carcinoma (ESCC) is a type of esophageal carcinoma (EC) that can affect any part of the esophagus, but is usually located in the upper or middle third. "To determine if ELK3’s regulation of the invasion and migration abilities in esophageal squamous cell carcinoma cells is linked to RHBDD1, we performed experiments with overexpressed RHBDD1 and downregulated ELK3." (PMID 40787199, 2025). "Collectively, these results establish RHBDD1 as a potential driver of proliferation, survival, invasion, migration, and metastasis in esophageal squamous cell carcinoma." (PMID 40787199, 2025). "Rhomboid domain containing 1 (RHBDD1) has been reported to play an important role in the development and progression of various cancers, but its role in esophageal malignancy is poorly understood, and this paper aims to explore the role of RHBDD in esophageal squamous cell carcinoma." (PMID 40787199, 2025).
lymph node metastasis (1 paper, 2015). "Moreover, the result that RHBDD1 expression was positively correlated with pTNM and pN classification indicates a potential correlation between RHBDD1 and malignancies with lymph node metastasis." (PMID 26300397, 2015).
Lymphatic Metastasis (1 paper, 2018). Transfer of a neoplasm from its primary site to lymph nodes or to distant parts of the body by way of the lymphatic system. "In 539 patients, the percentage of patients with positive RHBDD1 expression is higher (P < 0.001) among those with lymphatic metastasis than patients without lymphatic metastasis, and the intensity score of RHBDD1 is also significantly higher (P < 0.001) in patients with lymphatic metastasis." (PMID 29426364, 2018).
triple-negative breast carcinoma (1 paper, 2018). An invasive breast carcinoma which is negative for expression of estrogen receptor (ER), progesterone receptor (PR), and human epidermal growth factor receptor 2 (HER2). "The correlation between RHBDD1 expression and relapse-free survival in triple negative breast cancer patients (n = 161, p = 0.03, log-rank test)." (PMID 30286765, 2018).
tumor (12 papers, 2015 to 2025). "We then sought direct evidence that the decreased tumor cell growth associated with RHBDD1 inactivation was due to decreased TGFα/EGFR signalling." (PMID 26300397, 2015). "The results showed that RHBDD1 expression was closely associated with higher pathological tumor-node-metastasis (pTNM) stage (N=539, the χ2 test, P=0.0001), higher pathological node (pN) classification (N=539, the χ2 test, P=0.0002) and lower differentiation (N=539, the χ2 test, P=0.006)." (PMID 26300397, 2015). "Enhanced expression of RHBDD1 in ESCC cells significantly increased tumor cell invasion and migration." (PMID 40787199, 2025). "Then we analyzed the expression of RHBDD1 mRNA in TCGA datasets and found that RHBDD1 was higher in tumor tissues than normal tissues in PDAC." (PMID 41041073, 2025). "Previous studies have also shown that RHBDD1 in-fluences tumor metastasis via the Wnt/β-catenin signaling pathway." (PMID 40787199, 2025). "Among the predicted target genes, RHBDD1 was of special interest to us for it was reported to be tumor cell metastasis." (PMID 33041671, 2020). "We proved that RHBDD1 and ZEB1 were positively correlated at the protein level by western blotting and microarray assays in tumor tissues, which will further facilitate translational medicine research on RHBDD1." (PMID 29426364, 2018). "In the present study, we investigated the role of rhomboid domain containing 1 (RHBDD1) in tumor metastasis of CRC." (PMID 29426364, 2018). "For tumor grade, the R value was much higher in the II-III/III group, indicating that RHBDD1 and EGFR expression was significantly associated with advanced-stage tumor grade." (PMID 28445956, 2017). "In summary, our current findings demonstrate a novel role for RHBDD1 in promoting tumor cell growth through the ADAM-independent cleavage and secretion of proTGFα to activate the EGFR/Raf/MEK/ERK signalling pathway in CRC." (PMID 26300397, 2015). "Accordingly, the weights of tumours from RHBDD1-mutant HCT116 and RKO cells decreased more than 2- and 3-fold, respectively, compared with those originating from wild-type cells." (PMID 26300397, 2015). "The result revealed a statistically significant increase in RHBDD1 expression in tumours compared with normal tissues (N=16, the Student's two-tailed t-test, P<0.001)." (PMID 26300397, 2015). "More importantly, the plasma membrane localization suggests a potential role for RHBDD1 in tumor cell growth that differs from our previous findings." (PMID 26300397, 2015). "The role of RHBDD1 in reducing tumor cell growth was further validated by gene knockdown experiments." (PMID 26300397, 2015). "Taken together, these in vitro and in vivo experiments demonstrate that RHBDD1 inactivation inhibits tumor cell growth and that this inhibition can largely be attributed to the RHBDD1-mediated positive regulation of cell proliferation." (PMID 26300397, 2015). "Strikingly, we found that RHBDD1 inactivation inhibited tumor cell growth in proliferation assays and colony formation assays." (PMID 26300397, 2015). "Above results suggested that miR-924 might serve as a tumor suppressor by targeting RHBDD1 via deactivation of the Wnt/β-catenin pathway in NSCLC." (PMID 33041671, 2020). "We identified both known and novel somatic copy number aberrations (12p, MDM2, and RHBDD1) and mutations (XRCC2, PIK3CA, RITA1) including candidate markers for platinum resistance that were present in a primary tumor of mixed histology and that remained after tandem autologous stem cell transplant." (PMID 30870501, 2019). "We speculate that one mechanism may involve the different expression level of RHBDD1 in tumor and normal cell lines." (PMID 30286765, 2018). "Furthermore, EGFR and c-Jun were attenuated in the RHBDD1 knockdown and inactivated groups in animal tumor models." (PMID 28445956, 2017). "We observe that inactivation of RHBDD1 decreases tumor cell growth." (PMID 26300397, 2015).
tumor (continued). "Therefore, the correlation between RHBDD1 expression and tumor differentiation supports our study on the growth-promoting effect of RHBDD1 in tumor cells." (PMID 26300397, 2015). "The result that higher RHBDD1 expression was closely related to lower differentiation may imply a potential relationship between RHBDD1 and tumor growth." (PMID 26300397, 2015). "We next observed the subcellular localization of RHBDD1 in tumor cells." (PMID 26300397, 2015). "However, the tumor-restricted expression pattern of RHBDD1 renders this protease more important in tumorigenesis when compared with TACE which is widely expressed in tissues." (PMID 26300397, 2015). "The finding that proTGFα could be cleaved and activated by RHBDD1 in a dose-dependent manner in the presence of TACE further supports the idea that the increased RHBDD1 expression promotes the abnormal tumor cell growth." (PMID 26300397, 2015). "On the basis of our data, we speculate that one mechanism may involve proTGFα activation via the high expression of RHBDD1 in tumours." (PMID 26300397, 2015). "However, we found that RHBDD1 inactivation significantly inhibited tumor cell growth in vitro and in vivo and that this inhibition could largely be attributed to the RHBDD1-mediated positive regulation of cell proliferation." (PMID 26300397, 2015). "Therefore, the mechanism for RHBDD1 in promoting tumor cell growth was further explored." (PMID 26300397, 2015). "Further studies will address whether RHBDD1 plays a similar role in other tumours." (PMID 26300397, 2015). "The expression of CSE1L, LOX, RHBDD1, RRBP1 and SOGA1 was significantly higher in tumors than in tumor-adjacent tissue, and the survival analysis of each gene reached the same conclusion." (PMID 36421795, 2022). "Consistent with the in vitro experiments, the expression levels of RHBDD1, Wnt1, β-catenin and p-GSK-3β were down-regulated in the tumor xenografts of mice in the miR-924 mimic group compared with miR-NC group." (PMID 33041671, 2020). "In summary, our present study suggested that miR-924 function as a tumor suppressor in NSCLC cells by inhibiting cell proliferation, migration and invasion, at least in part, be ascribed to the negative regulation of RHBDD1 through Wnt/β-catenin signaling pathway." (PMID 33041671, 2020). "In contrast, reduced expression of RHBDD1 by knock-down experiment did not affect the proliferation rate of non-tumor HEK 293 T cells." (PMID 30286765, 2018). "To further determine whether RHBDD1 affects tumorigenesis in vivo, we subcutaneously injected wild-type and RHBDD1-mutant HCT116 and RKO cells into nude mice and monitored tumor growth." (PMID 26300397, 2015). "The tumours originating from wild-type HCT116 and RKO cells reached over 1,500 mm3 and 1,200 mm3, respectively, within 23 days, whereas the tumours originating from RHBDD1-mutant cells were <600 mm3 at the end of the experiment." (PMID 26300397, 2015). "RHBDD1 and EGFR were correlated regardless of the pathological parameters, including age, gender, tumor size, tumor grade and TNM stage." (PMID 28445956, 2017). "In this study, we also had not detected any apoptosis in RHBDD1-mutant HCT116 and RKO cells and even in the tumours derived from these mutant cells." (PMID 26300397, 2015).
cancer (10 papers, 2015 to 2025). A tumor composed of atypical neoplastic, often pleomorphic cells that invade other tissues. "Among the numerous molecules implicated in cancer pathogenesis, Rhomboid domain containing 1 (RHBDD1) has garnered increasing attention due to its multifaceted role in tumorigenesis." (PMID 40787199, 2025). "While Rhomboid domain containing 1 (RHBDD1) has been implicated in the progression of various cancers, its specific role and clinical relevance in ESCC pathogenesis are poorly understood." (PMID 40787199, 2025). "More recent studies have identified RHBDD1 as a crucial gene targeted by specific microRNAs (MiR-924), further underscoring its significance in cancer progression." (PMID 40787199, 2025). "In ESCC cells, elevated levels of RHBDD1 were correlated with enhanced cell proliferation and diminished apoptotic activity, leading to a more malignant cancer profile." (PMID 40787199, 2025). "The process of EMT, crucial in cancer cell transformation and metastasis promotion, is regulated by several factors, includ-ing RHBDD1." (PMID 40787199, 2025). "Given that epithelial–mesenchymal transition (EMT) is involved in cancer metastasis and invasion, the effects of RHBDD1 silencing on the expression of EMT-related genes were assessed." (PMID 30483390, 2018). "Most studies on RHBDD1 have concentrated on its role in cell proliferation and apoptosis in various cancers." (PMID 30483390, 2018). "By using small molecules, siRNAs, or RNA aptamers or inhibitors targeting RHBDD1 may be another potential method to treat cancers." (PMID 28445956, 2017). "In our study, the comparative results indicated that TACE and RHBDD1 could both individually drive proTGFα cleavage and secretion in cancer cells." (PMID 26300397, 2015). "In this study, we determined that RHBDD1 is positively correlated with CRC lymphatic metastasis and distal metastasis in clinical samples, thus proving its role in cancer metastasis." (PMID 29426364, 2018). "RHBDD1 is overexpressed in CRC, and EGFR is overexpressed in many cancers." (PMID 28445956, 2017).
RHBDD1 also shares sentences with these, for which no sentence is quoted: hepatocellular carcinoma (3 papers); chronic myeloid leukaemia (2); glioblastoma (2); alcohol abuse (1); Depression (1); digestive system tumours (1); invasive breast carcinoma (1); invasive ductal breast carcinoma (1); invasive lobular breast carcinoma (1); lobular breast carcinoma (1); lymphatic disease (1); prostate carcinoma (1); rectal cancer (1); seminoma (1).